CCL16 (C-C motif chemokine ligand 16)
Diseases named in the same sentence as CCL16 in open-access papers (continued):
Sharing a sentence is not in itself a finding about the gene and the disease.
pneumonia (1 paper, 2021). An acute, acute and chronic, or chronic inflammation focally or diffusely affecting the lung parenchyma, caused by an infection in one or both of the lungs (by bacteria, viruses, fungi, or mycoplasma.). "The role of CCL16 in cell model of pneumonia in human lung fibroblast cells was further detected, as well as the influence of miR-30b-5p expression on this role." (PMID 33817304, 2021). "Data from RT-qPCR and western blotting depicted a considerably higher level of CCL16 in the serum from patients with pneumonia (n = 30)." (PMID 33817304, 2021). "CCL16, a liver-expressed chemokine, belongs to human CC chemokines, which play a key role in pneumonia development." (PMID 33817304, 2021). "Then, the expression status of CCL16 in pneumonia was established." (PMID 33817304, 2021). "Besides, the key signaling pathways including NF-κB and TLR4 were discovered to be highly induced in LPS-induced pneumonia in WI-38 cells, and this activation was suppressed by silencing CCL16, which was consistent with previous data." (PMID 33817304, 2021). "Expression of XIST and CCL16 was upregulated in the serum of patients with pneumonia and LPS-induced WI-38 cells, respectively; silencing XIST and CCL16 could suppress LPS-induced apoptosis and inflammation in WI-38 cells, and this protection was abolished by miR-30b-5p downregulation." (PMID 33817304, 2021). "Therefore, CCL16 was a potent candidate for the target of XIST/miR-30b-5p axis in pneumonia." (PMID 33817304, 2021). "Moreover, there has been a negative correlation between CCL16 and miR-30b-5p expression in patients with pneumonia (Spearman’s rank correlation analysis, r = 0.5682, P < 0.001)." (PMID 33817304, 2021).
preeclampsia (1 paper, 2014). Preeclampsia is a hypertensive disorder of pregnancy that is characterized by new-onset hypertension with proteinuria presenting after 20 weeks of gestation, and depending on mild or severe forms may initially present with severe headache, visual disturbances, and hyperreflexia. "Furthermore, umbilical artery chemokine CCL16 and CCL24 levels were significantly higher in preeclampsia cords." (PMID 25485631, 2014).
prostate carcinoma (1 paper, 2024). A carcinoma that arises from epithelial cells of the prostate gland. "Additionally, elevated CCL16 (ligand of CCR1) expression exerted anticancer effects in mice with breast, colon, and prostate cancers." (PMID 38552222, 2024).
respiratory infections (1 paper, 2024). "Additionally, CXCR6/CCL16 regulates resident memory T cell localization to various lung compartments and maintains resident memory T lymphocytes in the airways, which serve as an essential initial line of defense against respiratory infections." (PMID 38922530, 2024).
sarcoma (1 paper, 2007). A usually aggressive malignant neoplasm of the soft tissue or bone. "A recent study showed that CCL16 stimulated cell migration of human osteogenic sarcoma cells expressing CCR1." (PMID 17506907, 2007).
Sepsis (1 paper, 2016). Sepsis is defined as life-threatening organ dysfunction caused by a dysregulated host response to infection. "Subsequent elevation of the genes encoding the inflammatory chemokines such as CCL16, CCL25 and CXCL6, and cytokines such as IL-2, IL-8 and IFNG in concert with delayed activation of the coagulation system are the typical signatures of sepsis." (PMID 27003632, 2016).
cancer (21 papers, 2007 to 2025). A tumor composed of atypical neoplastic, often pleomorphic cells that invade other tissues. "CCL16 also causes the migration of cancer cells if they exhibit CCR1 expression." (PMID 33182504, 2020). "The findings present convincing proof that cancer cells attract macrophages and support their M2 polarization by releasing CCL16." (PMID 38274805, 2023). "Some chemokine receptors, such as cCCL27 (8 cancers), CCL28 (7 cancers), CCL16 (5 cancers), CCL17 (5 cancers), and CCL15 (four cancers), were negatively associated with pyroptosis in several cancers." (PMID 35246158, 2022). "Based on the totality of our findings, we propose the following model: CCL16 (a potential cancer stemness gene) binds to the CCR2 receptor and activates p-AKT/GSK3β signaling, which enhances β-catenin stability and promotes β-catenin nuclear translocation." (PMID 33500726, 2021). "In regard to upstream events, we found that IL10 activates STAT3, which binds to the CCL16 promoter gene and enhances CCL16 expression, thereby increasing cancer cell stemness." (PMID 33500726, 2021). "To further evaluate the role of CCL16 in cancer cell stemness, we constructed an shRNA-resistant CCL16 (CCL16R) and stably expressed CCL16R in MDA-MB-231-shCCL16 and BT549-shCCL16 cells." (PMID 33500726, 2021). "The most researched ligand has been CCL16 whose increased expression has shown an anti-cancer effect in mouse breast cancer, and colon carcinoma, and prostate cancer due to an increase in the infiltration of the tumor by CD4+ T cells, CD8+ T cells, and DC." (PMID 33182504, 2020). "Another pro-cancer property of CCL16 is the induction of angiogenesis, related to the expression of its receptor CCR1 on vascular endothelial cells." (PMID 33182504, 2020). "Furthermore, comprehensive pan-cancer analysis indicated that GPR141 expression exhibited substantial associations with numerous chemokine family members, excluding CCL1, CCL16, and CCL27." (PMID 40959105, 2025). "As a seven-transmembrane G protein-coupled receptor, CCR5 can bind to a variety of ligands CCL3 (MIP1α), CCL3L1, CCL4 (MP-1β), CCL5 (RANTES), CCL8 (MCP2), CCL11 (Eotaxin), CCL13 (MCP-4), and CCL16, which are reported to be highly expressed in most malignant tumors." (PMID 36167571, 2022). "However, the functional role of CCL16 in other cancer types still remains an area for further study." (PMID 33500726, 2021). "Likewise, Stattic (a STAT3 phosphorylation inhibitor) deactivates STAT3 and suppresses CCL16 expression, thereby decreasing CCL16-mediated cancer cell stemness." (PMID 33500726, 2021). "In addition, shRNA silencing CCR2 and XAV939 (a β-catenin inhibitor) both abolish CCL16-mediated cancer cell stemness." (PMID 33500726, 2021). "In addition, shRNAs targeting CCR2 and XAV939 targeting β-catenin abolished CCL16-mediated cancer stemness." (PMID 33500726, 2021). "On the other hand, CCL16 enhances the anti-cancer effects of cytotoxic T and dendritic cells (DC) lymphocytes and some consider the possibility of using of this chemokine for enhancing the anticancer response in cancer immunotherapy." (PMID 33182504, 2020). "The precise roles of CCL16 in the bovine endometrium are currently unknown, but there is considerable information regarding its functions in immunological disease and cancer in humans." (PMID 28362325, 2017). "However, the role of CCL16 in cancer remains uncertain, which led to our present study." (PMID 33500726, 2021). "For other chemokines, CXCL11 was positively related to approximately all other chemokines except CCL14, CCL15, CCL16, CCL27, CCL28, CXCL6, and CXCL17 in almost all types of cancers." (PMID 35935945, 2022). "We identified several novel candidate genes (e.g., ICAM3, CCL16, PDE3A, and PRTN3) and showed that ICAM3 mediates cancer cell stemness as well as cancer-related inflammation via Src/PI3K/AKT signaling." (PMID 33500726, 2021).
cancer (continued). "Correlation analysis between RFC4 and checkpoint gene expression in different types of cancers showed a high correlation with immune genes including CCL4, CCL16, HLA family genes, TNFRSF8, TNFRSF14, TNFRSF18, CD70, CD44 (p < 0.05), CD276, CX3CL1 and VGEGFA (p < 0.05)." (PMID 39031628, 2024). "Moreover, we found that USP5 showed certain correlation with majority of chemokines with the exception of CCL1, CCL16, CCL27, CCL24 and CCL25 in pan-cancer." (PMID 37268697, 2023). "Another recent study has shown that CCL16 binds explicitly to CCR2, which in turn activates the AKT/mitogenic effector kinase (GSK3β) signaling and promotes β-catenin nuclear translocation, leading to enhanced cancer cell stemness." (PMID 35281057, 2022). "CCL16, a ligand of CCR1, accelerates the anti-cancer impacts of DCs and macrophages." (PMID 34737767, 2021). "The precise roles of CCL16 and CCL21 in the endometrium are currently unknown, but there is considerable information regarding their functions in immunological disease and cancer." (PMID 17506907, 2007). "Additionally, our analysis of chemokines revealed a strong positive correlation between EXO1 expression and CCL7, CCL13, and CCL18 in BRCA, OV, THCA, and UCEC, while a negative correlation was observed with CCL14 and CCL16 in most female-related cancers." (PMID 40433389, 2025). "CCL15, CCL14, CCL16, CCL23, and CCL27 showed negative relations in more than 10 cancers." (PMID 38655053, 2024).
tumor (16 papers, 2011 to 2025). "Some chemokines were increased in LSCC samples, such as CCL2, CCL15, CCL16, and these chemokines were implicated in the angiogenesis or angiostasis balance and promoted tumor infiltrating hematopoietic cells in the pathophysiology of NSCLC." (PMID 33005178, 2020). "Treg-associated chemokine receptor CCR8 ligands, CCL8, CCL16 and CCL18, were also elevated in tumour tissue stellate, epithelial and endothelial cells." (PMID 39915477, 2025). "Results from a luciferase assay show that XAV939 decreased CCL16-promoted tumor growth and tumor progression in vivo." (PMID 33500726, 2021). "We found that mice inoculated with 1 × 104 CCL16-overexpressing MDA-MB-231 cells demonstrated a dramatically increased incidence of tumor initiation versus mice inoculated with control cells and that CCR2 knockdown prevented this increased tumor incidence." (PMID 33500726, 2021). "Since the clinical pathological grade of a tumor closely correlates to tumor malignancy/differentiation, we explored the correlation between CCL16 immunostaining and pathological grade (grades 1, 2, and 3)." (PMID 33500726, 2021). "In this regard, a previous report indicated that CCL16 mediates the recruitment of immune cells and induces anti-tumor immunity." (PMID 33500726, 2021). "The STAT3-targeted inhibitor Stattic suppressed CCL16 expression in vitro and restrained tumor progression in vivo." (PMID 33500726, 2021). "We found that NOD/SCID mice inoculated with 1 × 105 CCL16-knockdown cells had dramatically decreased incidence of tumor initiation than mice inoculated with control cells." (PMID 33500726, 2021). "Whilst the expression of the Treg-associated chemokines, CCL8 and CCL16, was observed in non-immune cells, including epithelial cells (which includes the tumour cells), the highest expression of these chemokines was within the myeloid MoMac and DC populations." (PMID 39915477, 2025). "This interaction suggests that CCL16 could influence the tumor microenvironment by recruiting immune cells, such as macrophages, through the activation of these receptors." (PMID 38274805, 2023). "Furthermore, CCL16 exhibited potent myelosuppressive activity and markedly induced tumor rejection by promoting APC-T cell cross-talk." (PMID 35281057, 2022). "CCL16 was upregulated in breast tumors and closely correlated with tumor progression." (PMID 35281057, 2022). "In addition, CCL16 ectopic expression significantly stimulated tumor growth and tumor volume, which was prevented by CCR2 knockdown." (PMID 33500726, 2021). "In addition, we showed that Stattic blocks CCL16 expression in vitro and limits tumor progression in vivo." (PMID 33500726, 2021). "In addition, knockdown of CCL16 significantly reduced both tumor growth and tumor volume." (PMID 33500726, 2021). "CCR5 binds many ligands which are overexpressed in the tumor microenvironment including CXCL13 (BCA-1), CCL3 (MIP1α), CCL3L1, CCL4 (MP-1β), CCL8 (MCP2), CCL11 (eotaxin), CCL13 (MCP-4), and CCL16 (HCC-4)." (PMID 33485378, 2021). "Consistently, when CCR1 was knocked down in THP1 cells, co-culture with tumor cells overexpressing CCL16 no longer facilitated macrophage recruitment." (PMID 38274805, 2023).
immune disorders (1 paper, 2021). "Our results showed a panel of three downregulated miRNAs (hsa-miR-4516, hsa-miR-494-3p and hsa-miR-542-3p) involved in the regulation of genes associated with viral latency (SUPT16H, TFPI), HIV reactivation (PIM1) and persistent metabolic and immune disorders (ZADH2, CCL16)." (PMID 34829855, 2021).
infection (1 paper, 2024). The state of being infected such as from the introduction of a foreign agent such as serum, vaccine, antigenic substance or organism. "The overlap between patient samples collected during late acute phase and A549 infection included genes involved in response to immune stimulus such as CCL16 and IGHG1." (PMID 39065267, 2024).
neurological disease (1 paper, 2016). "Thirdly, we present 19 protein control concentration values, four of which (sortilin, CCL16, cystatin B, KLK5) have not, to our knowledge, previously been reported for adult individuals without neurological disease." (PMID 26914813, 2016).
CCL16 also shares sentences with these, for which no sentence is quoted: autoimmune disease (1 paper); benign tumors (1); chronic hepatitis B (1); colorectal carcinoma (1); glioma (1); neuroblastoma (1); ovarian carcinoma (1); pediatric Crohn's disease (1); renal disease (1); sarcoidosis (1); Stroke (1); systemic lupus erythematosus (1); type 1 diabetes (1); viral diseases (1).